INS (insulin)
Diseases named in the same sentence as INS in open-access papers (continued):
Sharing a sentence is not in itself a finding about the gene and the disease.
Hypoglycemia (continued). "Likewise, the limited and inconsistent reporting of hypoglycemia—together with short monitoring periods, conservative insulin titration strategies, and sparse or zero-event data in several trials—likely contributed to the modest or non-significant effects on TBR < 70 mg/dL and <54 mg/dL." (PMID 41517284, 2025). "This indicates that glucagon secretion may be dysregulated in some PCOS patients, which could have the dual role of countering hypoglycemia while also contributing to hyperinsulinemia via the stimulatory effects of paracrine glucagon signaling on insulin secretion." (PMID 40013621, 2025). "The most typical reasons for hypoglycemia were skipping meals while taking regular medications (511, 37.9%), consumption of sugar-reducing native food items (203, 15%) and taking higher doses of insulin (112, 8.3%) and oral medication (74, 5.5%) than prescribed." (PMID 40893590, 2025). "However, hypoglycemia induced by insulin overdose remains a clinical concern." (PMID 40362391, 2025). "While exogenous insulin helps control blood sugar, it often fails to prevent complications and may cause poor glycemic control or hypoglycemia." (PMID 40290901, 2025). "However, inadequate knowledge and malpractice on insulin self‐administration could result in poor treatment outcomes and insulin‐related complications like hypoglycemia." (PMID 40226177, 2025). "Nevertheless, NT5C-dKO mice displayed mild hypoglycemia and improved glucose clearance via 1) enhanced skeletal muscle insulin action, 2) lower hepatic glucose production (in the presence of metabolic stress), and 3) increased feeding-induced pancreatic insulin release." (PMID 39947478, 2025). "Thus, glyburide might lead to fetal overgrowth and neonatal hypoglycemia through excessive fetal insulin secretion, whereas metformin increases insulin sensitivity in the target organs without causing hyperinsulinism." (PMID 40235646, 2025). "Mechanistically, GLP-1 enhances glucose-dependent insulin secretion, suppresses glucagon release, and delays gastric emptying, whereas GIP primarily augments insulin secretion under hyperglycemic conditions but may stimulate glucagon secretion during hypoglycemia." (PMID 41404505, 2025). "Moreover, some clinical occasions, such as sepsis, alcohol intoxication, malnutrition, insulin overdose, or drug overdose, may present with hypoglycemia and the condition could be misinterpreted." (PMID 39968421, 2025). "Clinical doctors should adjust the insulin dose based on the degree of kidney function impairment when the eGFR drops below 60 mL/min/1.73 m2 to achieve blood glucose control goals as soon as possible while closely monitoring blood glucose and preventing hypoglycemia." (PMID 40114703, 2025). "Hypoglycemia was achieved using infusion of regular insulin and leading to rapid fluctuations in BG, which may not fully replicate the glycemic patterns seen with the intermediate‐ or long‐acting insulin formulations typically used in a clinical setting." (PMID 40105400, 2025). "However, these drugs, due to their continuous insulin secretory potential irrespective of glucose, lead to hypoglycemia and, if prolonged, cause pancreatic β-cell exhaustion and destruction that further worsens the diabetic condition." (PMID 40564164, 2025). "CIPII may be a therapeutic option in patients with severe subcutaneous (SC) insulin resistance, poor glycemic control with high daily insulin requirements, severe hypoglycemia and hypoglycemia unawareness during SC insulin therapy, skin disorders, SC site issues, lipohypertrophy and lipoatrophy." (PMID 40995084, 2025). "Hypoglycaemia is important—indeed without hypoglycaemia insulin doses could be titrated to normoglycaemia, and the risk of vascular complications from high glucose levels would vanish." (PMID 40035222, 2025).
Hypoglycemia (continued). "It is also possible that patients consume sweet beverages as a way to manage low blood glucose; however, hypoglycemia itself may also result from other factors, such as administering excessive insulin doses, improper dietary habits, or inaccurate carbohydrate counting." (PMID 41156556, 2025). "Additionally, it has been associated with small weight loss and lower daily insulin requirements without increasing hypoglycemia risk." (PMID 40707821, 2025). "Moreover, long‐term exposure to high CA could inhibit insulin secretion, along with surgical stress responses and fasting, which significantly increase the incidence of hypoglycemia following tumor removal." (PMID 40196048, 2025). "Non-insulin medicines are preferable to insulin in individuals who may be more susceptible to hypoglycaemia, or who may be reliant on others to administer the subcutaneous injection or may have reduced adherence with injectable formulations." (PMID 40651878, 2025). "However, insulin therapy must be implemented with extreme caution due to the substantial risk of severe hypoglycemia if insulin is administered without adequate concurrent glucose provision." (PMID 41463929, 2025). "Additionally, improper drug use could also contribute to hypoglycemia, particularly when used alongside insulin or insulin analogs and sulfonylurea hypoglycemic agents." (PMID 41282005, 2025). "Other aspects of self-care, such as insulin adherence, insulin dose calculation, diet and physical activity levels were not collected and could potentially be mediators between sleep quality and hypoglycemia." (PMID 40512259, 2025). "However, given that GDH also influences insulin regulation in pancreatic β cells, its persistent overactivation could lead to hyperinsulinemia and hypoglycemia." (PMID 40045666, 2025). "Importantly, the absence of severe hypoglycemic events in both cohorts implies that needle-free insulin delivery does not elevate the risk of hypoglycemia in the context of short-term intensive insulin therapy for T2DM patients." (PMID 41585790, 2025). "Despite the infrequency of hypoglycemia and irrespective of a lack of mortality associations with hypoglycemia in some studies, preventing hypoglycemia for patient safety is of utmost importance with insulin therapy and glycemic control procedures." (PMID 40944267, 2025). "Subcutaneous (SC) insulin delivery lowers blood glucose levels; however, inevitable episodes of hyper- and hypoglycaemia still occur due to slow or insufficient SC insulin uptake, overdosing, and systemic hyperinsulinemia, which may also alter plasma lipid profiles." (PMID 40755902, 2025). "On the other hand, patients on MDI insulin therapy may be more susceptible to hypoglycemia than AID users due to the lack of basal automation and may therefore require more frequent evaluations and adjustments of their insulin doses." (PMID 40004833, 2025). "Lack of frequent monitoring is the chief cause of hypoglycemia during insulin treatment." (PMID 41141170, 2025). "Indeed, incretin hormone action can reduce postprandial insulin secretion and improve hypoglycemia." (PMID 39264731, 2024). "But, in situations of insulin hypersensitivity, symptomatic hypoglycemia may occur." (PMID 38519536, 2024). "Our patient's fasting hypoglycemia could be caused by a probable defect in renal gluconeogenesis, not by stimulating pancreatic beta cells to secrete insulin." (PMID 38923174, 2024). "Increased insulin sensitivity in n3D-fed mice was also supported by the fact that when performing ITTs on 1.5-year-old female mice, only 2 of the 8 n3D-fed mice were able to finish the time course as all others had to be given a bolus of glucose due to hypoglycemia." (PMID 39566846, 2024). "Notably, our analysis showed that AI can cause hypoglycemia with lower insulin levels compared to patients without AI, emphasizing the need to consider AI in the management of RH." (PMID 39759743, 2024).
Hypoglycemia (continued). "Thus, evidence would suggest that IDeg-100 may be a better basal insulin option compared to Gla-100, with additional benefits in hypoglycemia prone T1DM population." (PMID 36896906, 2024). "However, considering the increase in total antioxidant capacity and the lack of significant results in the levels of MDA and SOD, it does not seem that oxidative stress plays a fundamental role in neurodegenerative injuries in rats subjected to severe insulin-induced hypoglycemia." (PMID 39004753, 2024). "However, hypoglycemia was still common in all age groups, so prospective studies characterizing individual variables are needed to facilitate tailored insulin dose adjustments that minimize glycemic variability while optimizing control in the diabetes camp setting." (PMID 39064653, 2024). "Moreover, hypoglycemia poses an obstacle for optimum control of diabetes, as the patient’s concerns of developing more hypoglycemic episodes would lead to avoidance of taking their insulin and other antihyperglycemic drugs." (PMID 39208059, 2024). "In this setting, the use of long-acting insulin analogues, when available, is more advisable than the use of classical human Neutral Protamine Hagedorn (NPH) insulin, as they provide less complex and more effective glycemic control with a reduced risk of hypoglycemia and glycemic variability." (PMID 38982528, 2024). "However, at least in our patient, there were periods of elevated ketones during prolonged fasting or after hypoglycemia despite elevated insulin levels, which may be related to some degree of impaired gluconeogenesis." (PMID 38279270, 2024). "In addition, more information on hypoglycemia treatment, pre- and postexercise insulin and carbohydrate advice, and an educational food guide which highlights the importance of low and high–glycemic index foods in the context of exercise was developed to be incorporated into the app." (PMID 39078700, 2024). "Insulin was not used in this case due to the concern of causing subsequent hypoglycemia, although in future cases may show a quicker return of normokalaemia and a normal heart rate compared to the current case." (PMID 39544913, 2024). "Our study found that the use of oral hypoglycemic agents or insulin is a predictor of hypoglycemia, which is consistent with previous studies in which it was reported that hypoglycemia is commonly caused by insulin, sulfonylurea, and non-sulfonylurea insulin secretagogues." (PMID 39610841, 2024). "Insulin therapy and non-White ethnicity were associated with developing inpatient hypoglycaemia." (PMID 38387535, 2024). "First published data from randomized trials using SGLT-2i in the treatment of patients with T1DM came from Canagliflozin and proved beneficial in metabolic control with a decrease in HbA1c and total insulin daily dose with no increased risk of hypoglycemia and decrease in body weight." (PMID 38396657, 2024). "In addition, a post hoc analysis of data from 2 of thephase 2 studies also found that hypoglycemia duration was similar with icodec comparedto IGlar U100 in insulin-naive and insulin-treated patients with T2D, regardless oftitration algorithm or use of a loading dose." (PMID 38224978, 2024). "Long-acting insulin may require a dose reduction to avoid hypoglycemia." (PMID 39149651, 2024). "These new insulins, by enabling earlier introduction of insulin, could result in an earlier reduction in HbA1c without an increased risk of hypoglycemia and contribute to preventing the onset or progression of chronic diabetes complications." (PMID 38559691, 2024). "Additionally, since insulin is anabolic to bone, there is a question as to whether there are indirect factors such as hypoglycemia-related falls that may drive fractures." (PMID 38887632, 2024).
Hypoglycemia (continued). "Antidiabetic drugs such as glyburide, gliclazide, insulin lispro, and insulin glargine are often combined with NSAIDs such as ASA and anticoagulants such as acenocoumarol (the last being dispensed only in our Catalonia data) to treat both conditions, which increases the risk of hypoglycemia." (PMID 38637816, 2024). "Furthermore, weight reduction and a decrease in the daily insulin dosage were observed with exenatide medication, all without raising the risk of hypoglycemia." (PMID 39273299, 2024). "We hypothesized that the impact of hypoglycemia on the fetal pancreas will have a global impact on genes related to growth and function as well as a direct impact on mRNA expression of glucagon and insulin." (PMID 38731997, 2024). "Moreover, one patient in the MTM group was on mixed insulin and was switched to aspart and glargine insulin to improve nocturnal hypoglycaemia; however, the number of insulin medications increased from 16 at the study entry to 17 at the end of the follow-up period." (PMID 39318717, 2024). "Although insulin dosing per se is based on CGM or capillary glucose levels, it has been proposed that individuals with a low MG but high HbA1c may be at increased risk of hypoglycaemia." (PMID 38668761, 2024). "However, a meta-analysis of 16 RCTs consisting of 7192 patients with T1DM found a reduction in the insulin requirements without an increased risk of hypoglycemia and diabetic ketoacidosis." (PMID 39861067, 2024). "So far, insulin Icodec has been demonstrated to be slightly better than daily administered basal analogs in terms of glucose control and the chance to achieve targeted glucose levels without a relevant gain in the risk of hypoglycemia in T2D." (PMID 39200316, 2024). "Plasma C-peptide positivity is well recorded and tends to associate with glycaemic control but does not always reflect a clinical effect and recipients that are insulin dependent may still experience hypoglycaemia and impaired awareness of hypoglycaemia even if C-peptide positive." (PMID 38169703, 2024). "However, the most common parental fear is related to hypoglycemia, which can be caused essentially by an inappropriate amount of insulin administration or lack of food intake." (PMID 39680256, 2024). "Furthermore, liraglutide showed an impact that spared insulin, lowering the daily insulin dose overall without raising the risk of hypoglycemia." (PMID 39273299, 2024). "However, intensive insulin management has been shown to be a risk factor for a higher frequency of hypoglycemic episodes but not severe hypoglycemia." (PMID 38397994, 2024). "Additionally, repetitive episodes of hypoglycaemia induced by insulin therapy or the presence of fear of hypoglycaemia may result in maladaptive eating habits that promote weight gain." (PMID 38341550, 2024). "The primary purpose of this study was to test the efficacy of two SSTR2 antagonists in a rodent model of T2D to see if treatment could enhance the endogenous glucagon counterregulatory response and prevent hypoglycemia during an insulin-induced hypoglycemic challenge." (PMID 38510652, 2024). "In some cases of hypoglycemia, a molar insulin/C-peptide ratio greater than 1 may occur." (PMID 39071705, 2024). "Given that non-vertebral fractures were associated with insulin users and falls, it was postulated that hypoglycaemia-related falls could be contributing to this observation." (PMID 38761257, 2024). "However, the clinical data presented here argue against hepatic glycogen depletion and impaired gluconeogenesis as the major driving factor for hypoglycemia, as all individuals presented with hyperinsulinemic hypoglycemia, strongly suggesting insulin secretory dysfunction." (PMID 38279270, 2024). "Notably, a large percentage of people with T1D do not follow the recommended prandial insulin injection timing, which can result in different glucose dynamics and increase both postprandial excursions and nocturnal hypoglycemia risk." (PMID 39062173, 2024).
Hypoglycemia (continued). "Consequently, the proportion of patients using MDI who may experience level 2 and level 3 hypoglycemia due to insulin accumulation was estimated to be 22%." (PMID 39411309, 2024). "However, this type of hypoglycemia can also result from defects in the insulin signaling pathway." (PMID 39483531, 2024). "Similarly, insulin users themselves may have experienced anxiety about hypoglycemia, leading to irregular treatment or self-adjustment of insulin dosages." (PMID 38969701, 2024). "Notably, patients who take multiple insulin injections may experience hypoglycemia due to relative hyperinsulinemia, as they cannot decrease their baseline insulin concentrations when taking a long-acting component." (PMID 38542818, 2024). "This may require reducing insulin doses by 25% on dialysis days to avoid hypoglycemia." (PMID 39149651, 2024). "Similarly, low SHR reflects episodes of hypoglycemia, which may be due to the incorrect use of insulin or antidiabetic drugs, prolonged fasting or digestive difficulties." (PMID 39502569, 2024). "Additionally, we found that TH protein expression was increased in the adrenal medulla following three episodes of insulin-induced hypoglycaemia, when measured at 60 min after the last episode, suggesting that long-term regulation of catecholamine synthesis is unlikely to be affected in HAAF." (PMID 38392992, 2024). "However, exercise can affect blood glucose levels, and adjustments in insulin doses and carbohydrate intake may be necessary to prevent hypoglycemia." (PMID 39310514, 2024). "Insulin injections are not ideal and have an increased risk of hypoglycaemia." (PMID 38168926, 2024). "Furthermore, the reduction in hypoglycaemia we observed following insulin/dextrose may have been influenced by other factors such as patient-related factors." (PMID 38871123, 2024). "While conventional insulin treatments like regular insulin and NBPH were groundbreaking at the time of their introduction, they often posed challenges, including unpredictable absorption, an increased risk of hypoglycemia, and less flexibility in dosing schedules." (PMID 39734941, 2024). "Interestingly, this effect is independent of insulin secretion and β-cell function, largely reducing the burden on β-cells and the risk of hypoglycemia." (PMID 38384297, 2024). "GLP-1 receptor agonists have also been shown to not elevate the risk of hypoglycemia when used independently, although their combination with insulin or sulfonylureas may increase this risk." (PMID 39574978, 2024). "However, about 5% of patients develop difficult-to-manage non-insulin-induced hypoglycemia." (PMID 39138498, 2024). "Skepticism toward the safety (e.g. fear of needles, hypoglycemia and/or weight gain) or efficacy of insulin, or the notion that insulin may result in social stigma or may be a punishment for failing self-care, are examples of potential beliefs involved when individuals with T2D oppose insulin." (PMID 38116986, 2024). "In conclusion, it seems that programming open-loop CSII devices with more than 4 basal insulin rates does not improve metabolic control; furthermore, it represents a potential risk factor for hypoglycemia and is an independent predictor of asymptomatic hypoglycemia." (PMID 38394157, 2024). "Therefore, providers could consider using a lower IV insulin rate (such as 0.05 units/kg/h) as glucose levels fall, to avoid hypoglycemia." (PMID 39136541, 2024). "Finally, we suggest that future studies consider assessing the HPA axis using expanded and complementary laboratory strategies, such as insulin-mediated hypoglycemia stimulation tests; CRH stimulation tests; or a combination of hair, saliva and/or blood measurements." (PMID 39585074, 2024). "In this study, the serum of TAA-intoxicated rats showed marked hypoglycemia, as TAA has a temporary impact on the liver’s ability to produce glycogen but later causes the glucose level to change, which disrupts pancreatic β-cells and increases insulin secretion." (PMID 36830960, 2023).